SLC25A11 (solute carrier family 25 member 11)
Description:
Catalyzes the transport of 2-oxoglutarate (alpha-oxoglutarate) across the inner mitochondrial membrane in an electroneutral exchange for malate. Can also exchange 2-oxoglutarate for other dicarboxylic acids such as malonate, succinate, maleate and oxaloacetate, although with lower affinity (By similarity). Substrate exchange across the membrane occurs consecutively with one substrate being transported first, then dissociating from the substrate binding site before the second substrate binds for transport in the opposite direction. Does not transport glutathione. In addition can facilitate proton transport in the presence of protonophores such as long-chain fatty acids, contributing to mitochondrial uncoupling and regulation of mitochondrial energetic efficiency (By similarity). Contributes to several metabolic processes, including the malate-aspartate shuttle, the oxoglutarate/isocitrate shuttle, gluconeogenesis from lactate, and nitrogen metabolism (By similarity). Maintains mitochondrial fusion and fission events, and the organization and morphology of cristae. Involved in the regulation of apoptosis (By similarity).
Synonyms: OGC; SLC20A4; PGL6; PPGL6
Tractability: Antibody: its Gene Ontology location is reachable by antibodies, with high confidence; UniProt predicts a signal peptide or a membrane-spanning region. PROTAC: ubiquitination databases record sites on it; its protein half-life has been measured.
Gene: Protein-coding gene on chromosome 17 (4,934,570 to 4,940,156, reverse strand). Ensembl gene ENSG00000108528.
Subcellular location: Mitochondrion inner membrane
Pathways (Reactome):
Metabolism: Malate-aspartate shuttle
Transport of small molecules: Organic anion transport by SLC5/17/25 transporters
Gene Ontology:
Molecular function: oxoglutarate:malate antiporter activity; protein binding; RNA binding; proton transmembrane transporter activity; alpha-ketoglutarate transmembrane transporter activity
Biological process: malate-aspartate shuttle; alpha-ketoglutarate transport; gluconeogenesis; malate transmembrane transport; proton transmembrane transport
Cellular component: mitochondrion; nucleus; mitochondrial inner membrane; plasma membrane
Genetic constraint (gnomAD): Loss-of-function variants: 11 observed, 34.57 expected, observed/expected ratio (o/e) 0.32, 90% interval 0.2 to 0.53. The upper end of that interval is the gene's LOEUF score, 0.53, which puts it in group 2 of 6, group 1 being the genes least tolerant of losing a copy. Missense variants: 295 observed, 445.97 expected, observed/expected ratio (o/e) 0.66, 90% interval 0.6 to 0.73. Synonymous variants: 163 observed, 178.55 expected, observed/expected ratio (o/e) 0.91, 90% interval 0.8 to 1.04.
Homologues: Orthologues: chimpanzee SLC25A11 (100% identical), dog SLC25A11 (97% identical), guinea pig SLC25A11 (97% identical), rat Slc25a11 (97% identical), rabbit SLC25A11 (97% identical), mouse Slc25a11 (96% identical), macaque SLC25A11 (94% identical), pig SLC25A11 (88% identical), tropical clawed frog rangrf (86% identical), zebrafish slc25a11 (85% identical), Caenorhabditis elegans misc-1 (67% identical), Drosophila melanogaster CG1907 (57% identical), and 2 more. Paralogues in human: SLC25A10 (36% identical), UCP1 (26% identical), SLC25A22 (25% identical), SLC25A14 (25% identical), UCP3 (25% identical), SLC25A34 (25% identical), SLC25A30 (24% identical), SLC25A12 (24% identical), SLC25A18 (24% identical), UCP2 (24% identical), SLC25A13 (24% identical), SLC25A21 (24% identical), and 37 more.